IL25 (interleukin 25)
Description:
Cytokine produced by various cells such as eosinophils, T-helper type 2 (Th2) cells or epithelial cells that plays a role in internal safety of adaptive immune responses by regulating cytokine production. Promotes and augments T-helper type 2 responses locally or systemically. Exerts its activity via its receptor composed of IL17RA and IL17RB for signal transduction (By similarity). In turn, stimulates the JAK2-STAT5A pathway and promotes the secretion of type-2 associated cytokines including IL4, IL9 and IL13. Also induces the release of IL8, and IL6 from eosinophils through the combined activation of MAPK and NF-kappa-B pathways. Inhibits the differentiation of T-helper (Th17) cells via the production of IL4, IL5 and IL13.
Synonyms: IL-25; IL-17E; IL17E
Tractability: Antibody: its Gene Ontology location is reachable by antibodies, with high confidence; UniProt places it where antibodies can reach, with medium confidence; UniProt predicts a signal peptide or a membrane-spanning region.
Gene: Protein-coding gene on chromosome 14 (23,372,809 to 23,376,403, forward strand). Ensembl gene ENSG00000166090.
Subcellular location: Secreted
Pathways (Reactome):
Immune System: Interleukin-17 signaling
Gene Ontology:
Molecular function: protein binding; interleukin-17E receptor binding; cytokine activity
Biological process: interleukin-17-mediated signaling pathway; protein K63-linked ubiquitination; regulation of keratinocyte proliferation; T-helper 17 type immune response; inflammatory response to antigenic stimulus
Cellular component: extracellular region; plasma membrane
Genetic constraint (gnomAD): Loss-of-function variants: 10 observed, 15.55 expected, observed/expected ratio (o/e) 0.64, 90% interval 0.4 to 1.09. The upper end of that interval is the gene's LOEUF score, 1.09, which puts it in group 4 of 6, group 1 being the genes least tolerant of losing a copy. Missense variants: 235 observed, 245.21 expected, observed/expected ratio (o/e) 0.96, 90% interval 0.86 to 1.07. Synonymous variants: 107 observed, 96.71 expected, observed/expected ratio (o/e) 1.11, 90% interval 0.94 to 1.3.
Homologues: Orthologues: chimpanzee IL25 (97% identical), macaque IL25 (92% identical), mouse Il25 (80% identical), pig IL25 (80% identical), rabbit IL25 (80% identical), rat Il25 (80% identical), guinea pig IL25 (79% identical), Caenorhabditis elegans F25D1.3 (16% identical). Paralogues in human: IL17D (24% identical), IL17C (24% identical), IL17F (20% identical), IL17A (19% identical), IL17B (19% identical).
Diseases named in the same sentence as IL25 in open-access papers:
IL25 is named in the same sentence as 207 diseases in open-access papers, as found by Europe PMC text mining. Sharing a sentence is not in itself a finding about the gene and the disease. The quoted sentences say what the papers report.
asthma (210 papers, 2008 to 2026). "Montelukast, a leukotriene receptor inhibitor used in the treatment of asthma, was associated with enhanced expression of IL-25 in airway epithelial cells." (PMID 40723867, 2025). "IL-25 has also been implicated in numerous models of allergic airway inflammation, including asthma, fibrosis, and CRSwNP." (PMID 41409758, 2025). "This review highlights the complex interplay of epithelial-derived alarmins, particularly TSLP, IL-33, and IL-25, in orchestrating the skewed T2 inflammatory phenotype that underlies the pathology in asthma." (PMID 39457624, 2024). "Th2 cells promote airway inflammation by production of a range of cytokines including IL-4, IL-5, IL-9, IL-13 and IL-25, which together are responsible for the development of hallmark features of asthma." (PMID 39598682, 2024). "Epithelial cytokines, in particular IL-25, have been implicated in asthma-associated angiogenesis, increasing the proliferation of endothelial cells at least in part by increasing VEGF/VEGF receptor expression." (PMID 38453256, 2024). "Twenty-four pathways in WT_IL-25/IL-33 transcriptomes were associated with cytokine–cytokine receptor interaction, asthma, arginine metabolism, proline, cysteine, methionine, glycine, serine, threonine, glutamine, and glutamate." (PMID 37337050, 2023). "We previously reported that epithelial IL-25 expression is associated with type 2 status and responsiveness to inhaled corticosteroids in asthma." (PMID 37898756, 2023). "Seys and colleagues evaluated sputum cytokine mRNA expression in an unselected group of adults with stable asthma, and demonstrated that higher levels of IL-5, IL-17A and IL-25 in the airways were associated with uncontrolled asthma and worse lung function." (PMID 35546400, 2022). "Of clinical relevance is the association of IL-25 production with asthma exacerbations triggered by respiratory viruses." (PMID 36311787, 2022). "Despite their overlapping function in asthma and inflammatory diseases associated with type 2 immunity, existing studies suggest that IL-25 and IL-33 elicit largely distinct immune pathways in CRC." (PMID 36263033, 2022). "IL-25 release by airway epithelial cells contributes to many other pathogenic features of asthma, including the recruitment of eosinophils, airway mucus over secretion, and airway remodeling." (PMID 35406669, 2022). "Hoverer, asthma comorbid AR patients showed an increase in the expression of systemic cytokine (IL-4, IL-5, and IL-25) in plasma; this was associated with a lower quality of life than that of patients with asthma." (PMID 35348596, 2022). "It is possible that if we examined cells from more donors and additional timepoints for 229E infection we would detect increased expression of IL-25 indicating that 229E, like RV, can stimulate type 2 inflammation and cause asthma exacerbation." (PMID 35508632, 2022). "Although the immunologic functions of IL-25 and IL-33 appear to overlap almost entirely, one large-scale genome-wide association study (GWAS) of asthma has indicated a more pronounced role for IL-33 in asthmatic patients." (PMID 35546400, 2022). "For instance, Toxocara spp larvae migrate to the lung and causing asthma-like symptoms, while IL-25 expression is one of the key cytokines for the development of asthma." (PMID 36119076, 2022). "The epithelium-derived cytokines IL-33, TSLP, and IL-25 have been implicated in pathogenesis of asthma because they promote type 2 cytokine synthesis." (PMID 35524325, 2022). "Activation of airway epithelium with allergens including Alt extract often causes severe asthma attacks and results in the release of several alarmins including IL-33, IL-25, GM-CSF, TSLP which orchestrate the downstream type 2 immune response." (PMID 34484177, 2021). "Recent studies show that ILC2 provokes inflammation in airways causing persistent asthma symptoms, which can be activated by IL-25." (PMID 34122457, 2021).
asthma (continued). "Recent studies revealed that cytokines such as thymic stromal lymphopoietin (TSLP), IL-33, and IL-25, highly expressed in the airway epithelium, are implicated in human asthma." (PMID 33445787, 2021). "Epithelial-derived cytokines such as thymic stromal lymphopoietin (TSLP), IL-25 and IL-33 are important factors in the pathogenesis of asthma as they promote Th2-associated immune responses via activation of DCs." (PMID 32477356, 2020). "IL-33 (ILC2 activator, besides TSLP and IL-25)) was also associated to airway remodeling in steroid resistant asthma." (PMID 31395084, 2019). "Epithelial cell-derived cytokines, including thymic stromal lymphopoietin (TSLP), IL-25, and IL-33 are critical regulators of innate and adaptive immune responses associated with Th2 cytokine-mediated inflammation in asthma." (PMID 28199345, 2017). "Anti-IL-25 agents, originally developed for treating respiratory viral infections, may also help manage severe asthma exacerbations associated with viral infections." (PMID 41169790, 2025). "IL-25 expression in the sputum of asthma patients is associated with asthma severity." (PMID 41169790, 2025). "IL-25 is another important cytokine implicated in the pathogenesis of asthma." (PMID 40723867, 2025). "Much more recently, Williams and colleagues demonstrated the beneficial role of IL-25 monoclonal antibodies in increasing antiviral responses, which could translate into the prevention of viral-associated asthma exacerbations." (PMID 40723867, 2025). "Moreover, a rare polymorphism in IL-17RB, the signaling receptor for IL-25, is associated with a reduced incidence of asthma." (PMID 39717777, 2024). "HRV infection can cause the release of pro-inflammatory factor IL-25 from respiratory epithelial cells, further promoting pulmonary production of type 2 immune/inflammation effectors IL-4, IL-5, IL-13, and IgE, to exacerbate asthma allergic responses." (PMID 38780281, 2024). "IL-33, like IL-25, has been found to be associated with virus-associated asthma exacerbations." (PMID 36311787, 2022). "IL-25 is a major driver for airway remodeling in asthma by causing increased epithelial damage, which then maintains eosinophil and immune cell infiltration by neutrophils and T cells and creates a positive feedback loop system that can perpetuate inflammation." (PMID 36311787, 2022). "Although IL-25 plays a relevant pathogenic role in allergic inflammation, to our knowledge no anti-IL-25 monoclonal antibody is currently in clinical development for add-on treatment of severe asthma." (PMID 33329598, 2020). "Since, RSV‐induced Th2 inflammation and airway responses were severely impaired in animals deficient in IL‐25 receptor (R) 11, IL‐25 may be a link between viral infections and development of asthma." (PMID 26734466, 2015). "A recent report indicates that these exposures may contribute to asthma symptomatology, since IL‐25 levels were associated with low lung function, high serum IgE, sputum eosinophils and responsive to corticosteroid response." (PMID 26734466, 2015). "We sought to assess whether the upper airway epithelium of patients with asthma may be an alternative source for the measurement of intracellular alarmin cytokines (TSLP, IL-25, and IL-33) in asthma and whether their expression is altered in association with asthma severity." (PMID 38999286, 2024). "Therefore, the RSV-induced inflammatory response was regulated by IL-25, which might reduce the severity of RSV-associated pulmonary inflammation and viral-induced asthma exacerbation via IL-25 blockade." (PMID 35008429, 2021). "In addition to asthma, IL-25 plays an important pathogenic role also in nasal polyposis." (PMID 34572294, 2021). "In contrast to T2-high asthma, epithelial-derived alarmins such as IL-33, IL-25, and TSLP play a less prominent role in T2-low asthma." (PMID 40806756, 2025).
asthma (continued). "Inhibition of IL-33 is being explored as a potential therapy for COPD, while IL-25 is being targeted in asthma and idiopathic pulmonary fibrosis." (PMID 41409758, 2025). "It is known that epithelial cells and innate lymphoid cells in airways of patients with asthma have an enhanced production of IL-13, IL-25, and IL-33 and a deficit in type I and III interferon responses that are needed for effective antiviral clearance." (PMID 39507925, 2025). "Obesity-driven upregulation of cytokines like IL-25 and TSLP in airway epithelium has also been implicated in asthma onset and progression." (PMID 40998975, 2025). "Thymic stromal lymphopoietin (TSLP), IL-33, and IL-25 are epithelial-derived proinflammatory alarmin cytokines that drive inflammatory airway diseases such as asthma and chronic obstructive pulmonary disease (COPD)." (PMID 41409758, 2025). "This is in line with our observation of significant increases in TSLP, IL-33, and IL-25 protein levels following T2 stimulation and viral infection, specifically in asthma-derived BECs." (PMID 40370530, 2025). "In asthma models, lung IL-25 levels are augmented by rhinovirus (RV) infection, and IL-25R blockade inhibits RV-induced exacerbation." (PMID 41409758, 2025). "Previous studies indicate that IL-25 has a proven role in asthma, and research is currently underway to assess its importance in other conditions, such as atopic dermatitis (AD) and inflammatory bowel disease (IBD)." (PMID 40981017, 2025). "In T2-high asthma, goblet cell metaplasia and epigenetic activation of alarmin (IL-25, IL-33, and TSLP) and Th2-related loci are prominent." (PMID 40806756, 2025). "Viral infections, another well-known trigger of asthma, have also been shown to increase the release of IL-25, IL-33 and IL-1β from epithelial cells." (PMID 39962262, 2025). "Clinical trials of anti-IL-25 efficacy for asthma or COPD have yet to demonstrate its role in modulating inflammation." (PMID 41409758, 2025). "This is the opposite effect to that seen in asthma, where high IL-25 levels are related to greater airway hyperresponsiveness, more airway and blood eosinophils, more subepithelial thickening, and the higher expression of T2-high signature genes." (PMID 39766355, 2024). "Exposure to inhaled asthma triggers causes the release of epithelial cytokines (TSLP, IL-25 and IL-33), which promotes both innate and adaptive T2 immune responses." (PMID 38453256, 2024). "Most attention has been given to the roles of IL-25 in allergic respiratory diseases, such as asthma and viral respiratory diseases, and IL-25 plays an important role in the beginning and progression of allergic diseases." (PMID 38785317, 2024). "While IL-25 serum levels in eCOPD patients were as high as in severe asthma, eotaxin-1 levels differed between groups." (PMID 39766355, 2024). "Three epithelial cytokines, i.e. thymic stromal lymphopoietin (TSLP), IL-33 and IL-25, known as “alarmins”, are central in asthma pathophysiology." (PMID 38609094, 2024). "IL-25, an epithelial-derived alarmin also known as IL-17E, is emerging as a promising therapeutic target for asthma, especially in patients with eosinophilic asthma." (PMID 38474348, 2024). "Among these, TSLP, IL-25, and IL-33 play pivotal roles as upstream regulators, initiating and amplifying inflammatory pathways that drive asthma symptoms, making them critical targets for therapeutic interventions." (PMID 39457624, 2024). "We conclude that airway tuft cells, by virtue of their production of IL-25, are required for the exaggerated asthma phenotype observed in immature mice undergoing repeated RV infections." (PMID 38061015, 2024). "IL-25 contributes to airway remodelling via the induction of airway angiogenesis in murine asthma models." (PMID 38609094, 2024). "We conclude that airway IL-25–producing tuft cells are required for the exaggerated asthma phenotype observed in immature mice undergoing repeated RV infections." (PMID 38061015, 2024).
asthma (continued). "It is commonly known that TSLP and other cytokines generated from epithelial cells, IL-25, and IL-33 are essential in the development of allergic disorders, such as food hypersensitivity, asthma, and AD." (PMID 39057040, 2024). "In nasal brushings, GINA 5 asthma patients expressed significantly higher levels of both TSLP and IL-25 when compared to all other asthma patients combined (GINA 1–4, p < 0.001 and p < 0.002, respectively, after adjusting for age and sex)." (PMID 38999286, 2024). "From these premises emerges the central role of IL-25 in the onset and exacerbation of a plethora of allergic inflammatory responses, including asthma, atopic dermatitis, and urticaria." (PMID 39767672, 2024). "TSLP, IL-25, and IL-33 are regarded as primary molecules involved in type 2 inflammatory response and have a crucial role in the pathogenesis of asthma." (PMID 39060923, 2024). "Regarding asthma, the most widely studied alarmins include IL-25, IL-33, and thymic stromal lymphopoietin (TSLP), which can all drive allergic inflammation via stimulation of TH2 cells and ILC2." (PMID 38878250, 2024). "Since DCLK1+ tuft cells are a major source of IL-25 in the gut, we examined the contribution of these cells to the RV-induced asthma-like phenotype in immature mice." (PMID 38061015, 2024). "Inhibition of the IL-25 pathway is also predicted to have similar clinical outcomes in asthma patients." (PMID 39717777, 2024). "In a cohort of severe asthma, IL-25 protein levels in sputum were significantly lower than control subjects." (PMID 37898756, 2023). "In patients with asthma, levels of type-2 instructional cytokines (IL-33 and IL-25) and effector cytokines (IL-4, IL-5, and IL-13) are elevated in the airway mucosa, associated with impaired antiviral immunity." (PMID 37174726, 2023). "While most of the FDA-approved biological therapies target pathways of T2 inflammation downstream of T-helper 2 cell activation, modest asthma control has led researchers to study upstream alarmin cytokines, including IL-25, IL-33, and TSLP." (PMID 38259298, 2023). "Innate cytokines, known as alarmins, specifically TSLP, IL-25, and IL-33, are promising candidates for the development of novel biological therapies against severe asthma." (PMID 38203353, 2023). "Tezepelumab is a fully human IgG2 mAb directed to the thymic stromal lymphopoietin —a cytokine of the alarmin family that, together with IL-25 and IL-33, is derived from epithelial cells and plays a very important role in the pathogenesis of asthma." (PMID 36836079, 2023). "Similar to the findings in sputum from severe asthma, the transcripts of IL-25 in bronchial epithelial brushings were significantly lower in subjects with non-eosinophilic asthma (n = 14) than those with eosinophilic asthma (n = 20)." (PMID 37898756, 2023). "Other studies have also proven that elevated IL-25 levels in asthma contribute to angiogenesis, at least in part by increasing VEGF/VEGF receptor expression in endothelial cells through the PI3K/Akt and Erk/MAPK pathways." (PMID 37174726, 2023). "In asthma patients, IL-25 has been found to increase the expression of endothelial VEGF/VEGF receptors through the PI3K/AKT and ERK/MAPK pathways." (PMID 37005677, 2023). "It has been well-documented that IL-25 is critically involved in the development of allergic disorders (e.g., asthma)." (PMID 37005677, 2023). "The bronchial epithelium integrates complex inflammatory and remodeling processes in asthma by releasing IL-25, IL-33, and thymic stromal lymphopoietin (TSLP)." (PMID 37635231, 2023). "In a mouse model of asthma, IL-25 was found to stimulate natural killer T cells to produce inflammatory factors (e.g., IL-13), thereby promoting airway hyperresponsiveness." (PMID 37005677, 2023). "Previous studies have shown that IL-25 levels are increased in patients with asthma with fixed airflow limitation (FAL)." (PMID 37635231, 2023).